INS (insulin)
Diseases named in the same sentence as INS in open-access papers (continued):
Sharing a sentence is not in itself a finding about the gene and the disease.
cancer (continued). "According to a cohort study, conducted in 2005 by Diabetes UK, The cancer risk and mortality is progressively elevating in insulin treated diabetic individuals." (PMID 28197516, 2016). "Excess adipose tissue works though many indirect mechanisms to cause insulin insensitivity and chronically elevated levels of serum glucose, which can lead to cancer progression and resistance to cancer treatments." (PMID 26977321, 2016). "Although insulin studies with cancer mortality as an endpoint are few, insulin therapy has been associated with an increased cancer incidence." (PMID 27031113, 2016). "Metformin is considered to play a protective role in cancer development and outcomes, whilst exogenous insulin use seems to be associated with an elevated cancer risk." (PMID 27724912, 2016). "The present study is probably the first to demonstrate a significantly higher risk of mortality from either cancer or non-cancer death associated with insulin use (Models I to III)." (PMID 27906989, 2016). "The risks of all-cause mortality, MACE and incident cancer were evaluated using multivariable Cox models comparing insulin monotherapy with insulin plus metformin." (PMID 27152598, 2016). "Reductions in insulin have been linked to a reduced risk of cancer reoccurrence and CVD, therefore improving health outcomes for participants." (PMID 27781180, 2016). "Insulin use was significantly associated with an increased risk of cancer (73 studies; RR = 1.21, 95% CI 1.08-1.36)." (PMID 26076034, 2015). "Previous studies demonstrated potential interconnected mechanisms involving excess adiposity and cancer risk, including insulin/insulin-like growth factor, circulating adipokines and systemic inflammatory mediators, sex steroids, and so on." (PMID 26061746, 2015). "Apart from intermediate-acting insulin, rapid-acting, long-acting, and combination insulin treatment significantly reduced the overall cancer risk among all DM patients." (PMID 25978841, 2015). "For two decades there has been an intensive debate about the human risk for increased cancer incidence when using insulin analogues." (PMID 25848982, 2015). "With regards to breast cancer, two genetic variations (MNTR1a and 1b genes) have been shown to be associated both with cancer susceptibility and perturbed expression of insulin and glucose." (PMID 26284119, 2015). "Of the 57 significant pathways, we frequently see four types of pathway, all of which have been previously linked with aging: insulin signaling; sugar and fatty acid metabolism; xenobiotic metabolism; and cancer-related pathways." (PMID 25758824, 2015). "Recently, pioglitazone (PGZ) was proposed to exhibit anti-cancer properties, including a reduction in insulin resistance and adipose tissue loss; nevertheless, few studies have evaluated its effect on survival." (PMID 25807446, 2015). "In other words, the insulin-lowering effect of metformin was associated with its anticancer effect, thereby having less of an impact on cancer in patients with normal or lower insulin levels." (PMID 25866823, 2015). "In particular, insulin concentrations and T2D have been associated with higher incidence and mortality from numerous cancers in observational studies." (PMID 26134033, 2015). "In epidemiologic studies, treatment with insulin or insulin secretagogues has been associated with an increased risk of some cancers, including breast, colon, pancreas, and prostate." (PMID 26250516, 2015). "In this section, we discuss the relationship between cancer risk and antidiabetic medication, including insulin and insulin analogs, metformin, and thiazolidinediones." (PMID 25866823, 2015). "Among patients with type 2 DM, insulin treatment is associated with a worse cancer outcome and increased all-cause mortality compared to metformin treatment." (PMID 26242987, 2015).
cancer (continued). "On the other hand, insulin signaling deficiency caused by the downregulation of IRs was shown to inhibit the proliferation and metastasis of cancer cells in vitro and in vivo." (PMID 25866823, 2015). "Increased circulating insulin levels over endogenous insulin secretion occur frequently with subcutaneous insulin injection, thereby making possible the association between insulin therapy and cancer." (PMID 25866823, 2015). "Although mainstream studies have suggested that insulin and IGFs are associated strongly with cancer development, each study showed a different degree of cancer risk associated with insulin and IGFs." (PMID 25866823, 2015). "The IR-A, considered the fetal IR isoform, primarily mediates the mitogenic effects of IGF-II and insulin, and is implicated in development and cancer, while the second IR isoform (IR-B) is prevalently involved in glucose metabolism of insulin target organs." (PMID 25840417, 2015). "Epidemiological studies have suggested that type 2 diabetic patients treated with metformin have lower risk of developing or dying from cancer relative to diabetic patients receiving sulfonylureas, insulin, or other therapies." (PMID 26029167, 2015). "In our study, half the deaths among type 2 diabetic subjects treated with insulin were due to a cardiovascular cause and one quarter was due to a cancer." (PMID 24752580, 2014). "It is important to point out that none of these variables were observed to confound the association between insulin use and cancer incidence." (PMID 25329887, 2014). "Insulin has been shown to induce glucose metabolism and associated with a variety of cancer development in solid tumors." (PMID 24895527, 2014). "In this scenario, the effects of insulin analogs on cancer risk are directly related to glucose control: subjects with poor metabolic control treated with relatively high (pharmacological) doses of an insulin analog especially run an increased risk for cancer." (PMID 24904529, 2014). "Increased glucose consumption is a hallmark of many cancer cells, and increased blood glucose and insulin levels seen in type II diabetes are associated with worse cancer prognosis." (PMID 25347702, 2014). "The debate is far from a closure, but the inverse dose-effect association for insulins and glargine insulin exposure in particular is an argument for their benign nature as regards cancer mortality risk." (PMID 24667573, 2014). "Of importance is that variations in the rates of insulin secretion have been shown to influence cancer risk and prognosis among individual patients." (PMID 24434591, 2014). "The top 1% of PD-miRNA were significantly enriched for regulation of genes involved in glucose/insulin metabolism and cell division (p < 10−7), most significantly the mitosis pathway, which is strongly linked to cancer onset." (PMID 25169894, 2014). "Some meta-analyses have shown that metformin use reduces while sulfonylurea and insulin use increases overall cancer risk." (PMID 24924771, 2014). "Increasing epidemiologic evidence suggests insulin effect on both the risk and the prognosis of cancer, but the effect is different in different cancer types." (PMID 24924771, 2014). "This study reported that the overall risk of cancer in patients treated with insulin glargine was about half that of patients with human insulin." (PMID 25329887, 2014). "Association between long-acting insulin use and cancer for new users by dose category (As-Treated Analysis)." (PMID 25329887, 2014). "It has also been demonstrated that humans with growth hormone receptor deficiency also exhibit a high reduction of IGF-1 and insulin level resulting in a highly reduced incidence of cancer and diabetes mortality." (PMID 24883306, 2014). "Insulin is an important growth factor for cancer cells and chronic hyperinsulinaemia has been associated with cancers of the colon, breast, pancreas, and endometrium." (PMID 24858012, 2014).
cancer (continued). "The two most thoroughly studied adipokines, adiponectin and leptin, have in fact been linked to the development of malignant tumors through their action on cognate receptors affecting insulin sensitivity and/or activating cancer-associated signaling." (PMID 24676332, 2014). "In contrast, the cytoplasmic or nuclear β-catenin observed in islet adenomas and carcinomas was accompanied with dramatic loss of insulin expression indicative of a tumorigenic transition." (PMID 25352948, 2014). "The mitogenic effects of elevated insulin and the energetic effects of elevated glucose were logical candidates as risk factors for cancer." (PMID 23405181, 2013). "There is evidence that plasma levels of insulin or the C-peptide, which is the peptide that is cleaved from insulin during its biosynthesis, are associated with colon, endometrial, breast, prostate and pancreatic cancers." (PMID 23983688, 2013). "The efficacy of insulin-lowering therapies in reducing risk and progression of cancer is highlighted by the converse, that is, increased risk of cancer in diabetic patients treated with insulin analogues." (PMID 23573093, 2013). "We now present evidence that human cancer xenotumors harboring the insulin-unresponsive PIK3CA-activating mutation H1047R remain sensitive to metformin." (PMID 23986086, 2013). "Insulin is one of the most commonly prescribed medications, and the interest in its role on cancer risk in diabetic patients has increased recently." (PMID 23308218, 2013). "Patients with type 2 diabetes exposed to sulfonylurea or exogenous insulin had a significantly increased risk of cancer-related mortality compared with patients exposed to metformin." (PMID 24131755, 2013). "Further, it has been shown that the duration of insulin treatment is associated positively with cancer incidence." (PMID 23983688, 2013). "The present systematic review and meta-analysis of published observational studies was conducted to assess the risk of cancer during treatment with insulin." (PMID 24175949, 2013). "A recent meta-analysis, including 562,043 participants and 14,085 cases of cancer, was published assessing the risk of cancer during treatment with insulin." (PMID 23401790, 2013). "PI3K is the chief mediator of insulin signalling in liver and is frequently mutated in liver and other cancers." (PMID 23837608, 2013). "In human studies, H2O2 was evaluated as a biomarker of ROS and showed high values in cancer patients, and associations with 8-OHdG, total cholesterol, and insulin dependency in healthy subjects." (PMID 24317383, 2013). "The association between insulin and cancer growth is linked at the biological level through hyperinsulinemia." (PMID 24282613, 2013). "All those epidemiological studies are affected by prescription bias: patients receiving a prescription for insulin therapy can be affected by conditions which increase the risk of cancer and cannot be accounted for in statistical adjustments." (PMID 24348585, 2013). "In this regard, the protopathic bias has been reported as the main factor accounting for the increased risk of cancer in the first 6 months after starting treatment with insulin and sulfonylureas." (PMID 24278227, 2013). "Epidemiological studies have consistently suggested that type 2 diabetic patients treated with metformin have a lower risk of developing and dying from cancer than do diabetic patients receiving sulfonylurea, insulin, or other therapies." (PMID 23986086, 2013). "The pathway, with oncogene PIK3CA and tumor suppressor PTEN (gene), is implicated in insensitivity of cancer tumors to insulin and IGF1, in calorie restriction." (PMID 23768168, 2013). "The combination of insulin with metformin limits weight gain, reduces insulin doses, and tampers potential risks of cancer associated with high-dose insulin." (PMID 24348585, 2013). "Epidemiological and biochemical studies establish the role of insulin and hyperinsulinaemia in cancer risk and progression." (PMID 23983688, 2013).
cancer (continued). "Numerous epidemiological studies reporting correlation of elevated C-peptide, postprandial, and fasting insulin levels with cancer risk were summarized and meta-analyzed." (PMID 23476808, 2013). "Metformin reduces the levels of circulating insulin and decreases the levels of glucose in the blood; it is probably through these effects that metformin decreases cancer risk." (PMID 23983688, 2013). "For example, we present below a recent prospective study of fasting serum insulin levels and the risk of three cancer case groups which involved a single subcohort." (PMID 23834739, 2013). "Insulin is tightly associated with cancer progression; however, mechanistic insights into such observations are poorly understood." (PMID 23837608, 2013). "It showed that insulin treatment was associated with an increased risk of overall cancer (RR (95% CI) = 1.39 (1.14, 1.70)) especially with pancreatic cancer (RR (95% CI) = 4.78 (3.12, 7.32))." (PMID 23401790, 2013). "Epidemiological studies addressing the link between the use of specific insulin analogs and cancer risk are so far inconclusive and face various interfering factors, including the heterogeneity of the diabetic population." (PMID 24115945, 2013). "The role of insulin in cancer promotion is suggested by studies associating circulating insulin levels and cancer of the colon, pancreas, and breast." (PMID 24278227, 2013). "Compared with other insulin analogues, insulin glargine use was associated with a lower odds of overall cancer in a random-effects model (OR 0.76, 95% CI 0.62 to 0.93, P = 0.008), with significant heterogeneity (P = 0.003, I2 = 79.0%)." (PMID 23284776, 2012). "In fact, the effect of insulin on cell proliferation in vitro is dose-dependent and the association of insulin therapy with cancer in epidemiological studies is related with dose and duration of treatment." (PMID 23209929, 2012). "Insulin has recently been implicated to have cancer promoting effects, while recent evidence suggests metformin to have cancer protecting effects in patients with type 2 DM." (PMID 22295251, 2012). "Our study found that diabetic patients treated with sulphonylurea or insulin monotherapy were at a significantly higher risk of cancers, compared to those treated with metformin." (PMID 22719752, 2012). "Among diabetic patients, those receiving insulin or sulphonylurea monotherapy are at a higher risk of cancer compared to those receiving metformin." (PMID 22719752, 2012). "Diabetic patients treated with insulin or sulfonylureas had significantly higher risk of all cancers, compared to those treated with metformin (OR: 1.583; 95% CI: 1.389–1.805, P < 0.001 and OR: 1.784; 95% CI: 1.406–2.262, P < 0.001)." (PMID 22719752, 2012). "It should also be considered that some studies, which happen to report a higher-than-average risk associated with insulin therapy, investigated cancer-related mortality instead of cancer incidence." (PMID 23209929, 2012). "Similar data have been reported in mice with cancer cachexia, in which severe weight loss is associated with decreased leptin and insulin, whereas resistin remains unchanged." (PMID 23781298, 2012). "The potentially alarming increase in cancer risk in insulin-treated patients suggested by many epidemiological studies, although supported by the results of in vitro investigations, has not been confirmed by randomized clinical trials." (PMID 23209929, 2012). "Increased interest in molecular safety of insulin analogues was stimulated by four epidemiological studies in this Journal in June 2009, three of which suggested an association between the use of insulin glargine (glargine) and cancer." (PMID 22590494, 2012). "Overall, epidemiological studies suggest a possible increase of risk with glargine, with respect to human insulin, only at high doses and for some forms of cancer (i.e., breast)." (PMID 23209929, 2012).
cancer (continued). "Patients receiving insulin or sulfonylurea had a higher risk of all cancers, compared to those receiving metformin (OR: 1.583, 95% CI: 1.389–1.805, P < 0.001 and OR: 1.784, 95% CI: 1.406–2.262, P < 0.001, resp)." (PMID 22719752, 2012). "Mounting studies have reported that elevated IGF or insulin in the serum correlated with increased risk of cancer development." (PMID 23112878, 2012). "The largest study of 127 031 patients reported an increase in the risk of cancer with higher doses and longer duration of exposure to any insulin and that after adjusting for insulin dose, insulin glargine-treated patients were at highest risk." (PMID 21410860, 2011). "We were unable to identify raised cancer risk among cohort members who took insulin analogues, either alone or in combination." (PMID 21752291, 2011). "This study is designed to examine cancer incidence associated with use of insulin glargine vs. intermediate/long-acting human insulin (HI)." (PMID 21738645, 2011). "Contrary to this finding, inverse associations for HOMA-IR and insulin with cancer recurrence were observed in the ER/PR-positive group with borderline significance (P for trend = 0.096 and 0.078)." (PMID 21450081, 2011). "miRNAs have been widely studied in cancer, where they can act as oncogenes or tumor suppressors, but they have also been associated with the regulation of genes involved with insulin secretion, cholesterol biosynthesis, fat metabolism, and adipogenesis." (PMID 21526116, 2011). "The incomparability between insulin glargine users and other types of insulin or oral anti-diabetic agent users raises the question about the most appropriate reference group in the studies of cancer risk and insulin." (PMID 21738645, 2011). "The first cohort results confirm previous reports on the association of T2D with cancer and the role of insulin therapy." (PMID 21752291, 2011). "A series of recently published epidemiological studies have attempted to investigate the effects of insulin use on cancer risk." (PMID 21410860, 2011). "A cohort study from Germany reported that the risk of overall cancer increased with dose for any type of insulin." (PMID 21738645, 2011). "Genetic studies showed that the risk of cancer is influenced by IGF/INS gene variants, and cancer-associated somatic copy number variations are found in IGF/INS gene regions." (PMID 20924377, 2010). "With respect to the recent commission by the EMEA "to further investigate the possible increased risk of cancer associated with the use of insulin glargine...", the safety profile of insulin glargine (Lantus®) was of particular interest." (PMID 21176129, 2010). "On the other hand, this condition appears strictly associated with the development of NPC-derived cancers mainly sustained by insulin secretion." (PMID 20436918, 2010). "Glycogen Synthase Kinase-3 (GSK-3) α and β are two serine-threonine kinases controlling insulin, Wnt/β-catenin, NF-κB signaling and other cancer-associated transduction pathways." (PMID 20920357, 2010). "In many human cancers, there is a strong association with dysregulated insulin/IGF signaling pathway that has been extensively reviewed." (PMID 20069126, 2010). "Analysis of associations between insulin and cancer risk, using prescription databases and cancer registries is complicated and should only be undertaken with extreme caution." (PMID 22276024, 2009). "Much has been done to evaluate the association between PPARγ2Pro12Ala polymorphism and body mass, insulin sensitivity, risk of T2D, cancer, and other aspects of human health." (PMID 19390629, 2009). "Previous to this, there had been no indication from in vivo or in vitro studies or in randomized trials that glargine insulin was associated with an increased risk of cancer." (PMID 24966880, 2009).